INPP5K (inositol polyphosphate-5-phosphatase K)
Diseases named in the same sentence as INPP5K in open-access papers:
INPP5K is named in the same sentence as 35 diseases in open-access papers, as found by Europe PMC text mining. Sharing a sentence is not in itself a finding about the gene and the disease. The quoted sentences say what the papers report.
Intellectual disability (8 papers, 2017 to 2024). "Mutations in INPP5K are associated with autosomal recessive congenital muscular dystrophy with cataracts and intellectual disability (MDCCAID)." (PMID 38559586, 2024). "INPP5K mutations in humans cause a distinct neurodevelopmental syndrome with variable presentation of intellectual disability, cataracts, short stature, and muscle disease." (PMID 37184573, 2023). "Mutations in inositol polyphosphate 5-phosphatase K (INPP5K) lead to a syndrome characterized by variable presentation of intellectual disability, brain abnormalities, cataracts, muscle disease, and short stature." (PMID 37184573, 2023). "Biallelic variants impairing catalytic activity of INPP5K have causally been associated with a form of congenital muscular dystrophy characterized by cataracts, cerebellar atrophy, epilepsy, intellectual disability, and short stature." (PMID 33193651, 2020). "Several reports have linked biallelic mutations in INPP5K to congenital muscular dystrophy with cataracts and intellectual disability (MIM 617404)." (PMID 31413155, 2019). "Mutations in INPP5K, the enzyme with 5-phosphatase activity toward PIs, were reported in patients suffering from congenital muscular dystrophy with cataracts and intellectual disability (MDCCAID) and short stature." (PMID 38559586, 2024). "As for the intellectual disabilities seen in patients, Dong and colleagues point out that these are consistent with the function of INPP5K in neurons." (PMID 31413155, 2019). "We identified bi-allelic missense and in-frame deletion mutations in INPP5K in eight families with a syndrome consisting of CMD, early-onset cataracts, and mild intellectual disability." (PMID 28190456, 2017). "All individuals with identified bi-allelic INPP5K mutations presented with a homogeneous clinical picture including both CMD and early-onset cataracts, usually with mild intellectual disability." (PMID 28190456, 2017). "Also, other genes encoding proteins of the inositol phosphatase metabolism (e.g., INPP5K, FIG4, INPP5E) are associated with autosomal recessive syndromes of intellectual disability." (PMID 33168985, 2021). "DYNLRB1 was found to be associated to neuronal survival, INPP5K was found to be associated to cognitive impairment, ZFHX2 was found to be associated to behavioral abnormalities and CTNND2 was found to be associated to mental retardation and intellectual disability." (PMID 33510859, 2021). "Although individuals with INPP5K mutations did not have cerebellar atrophy and ataxia, there was a clear phenotypic overlap with MSS (early cataracts, myopathy, cerebellar atrophy, variable intellectual disability)." (PMID 28190456, 2017).
congenital muscular dystrophy (6 papers, 2017 to 2024). A muscular dystrophy that is characterized by diminished muscle tone (hypotonia), progressive muscle weakness and degeneration (atrophy), abnormally fixed joints, spinal rigidity, and delays in reaching motor milestones such as sitting or standing unassisted. "Most recently, homozygous or compound heterozygous mutations in INPP5K, the focus of this report, were identified as causative for congenital muscular dystrophy." (PMID 33119550, 2021). "Missense INPP5K mutations are causative for congenital muscular dystrophy overlapping with Marinesco-Sjögren syndrome (MSS), in which affected individuals exhibit a constellation of clinical manifestations, including muscular dystrophy, cataracts, and variable penetrance of brain abnormalities." (PMID 33119550, 2021). "Moreover, mutations in INPP5K, which encodes the inositol polyphosphate-5-phosphatase K, also known as SKIP (skeletal muscle and kidney enriched inositol phosphatase), cause congenital muscular dystrophy, with LGMD and neuropathic features." (PMID 31680794, 2019). "Notably, mutations in humans that impair the phosphatase activity of INPP5K lead to congenital muscular dystrophy with additional clinical manifestations, including intellectual impairments, suggesting that INPP5K plays an important role in the nervous system to maintain proper function of neurons." (PMID 34556534, 2021).
cataract (5 papers, 2017 to 2024). Partial or complete opacity of the crystalline lens of one or both eyes that decreases visual acuity and eventually results in blindness. "In addition to Lowe’s syndrome, there is partial overlap between PIK3C2A deficiency and yet other Mendelian disorders of PI metabolism such as the early-onset cataracts in patients with INPP5K deficiency, demonstrating the importance of PI metabolism in lens development." (PMID 31034465, 2019).
muscular dystrophy (5 papers, 2017 to 2021). Muscular dystrophy (MD) refers to a group of more than 30 genetic diseases characterized by progressive weakness and degeneration of the skeletal muscles that control movement. "Biallelic pathogenic variants in INPP5K have recently been reported in patients affected by a form of muscular dystrophy with childhood onset." (PMID 33193651, 2020). "There are discrepancies concerning the effect of impaired INPP5K activity, leading to improved myoblast differentiation, contrasting with muscular dystrophy in individuals with INPP5K mutations." (PMID 28190456, 2017). "Muscular dystrophy caused by INPP5K mutations shows features suggestive of autophagy inhibition, including the accumulation of rimmed vacuoles, p62/SQSTM1, and αB-crystallin, but whether autophagy is impaired remains unresolved." (PMID 33119550, 2021). "Muscle pathology in inpp5ka+inpp5kb zebrafish morphants was also indicative of skeletal muscle degeneration, again supporting a muscular dystrophy in individuals with INPP5K mutations and reinforcing the view that zebrafish can be used to model neuromuscular conditions." (PMID 28190456, 2017). "Muscular dystrophy caused by INPP5K mutations exhibits histopathological features consistent with an autophagy-related muscle disorder, and here we showed that muscle-specific ablation of INPP5K in mice led to disease with autophagy inhibition caused by suppression of ALR." (PMID 33119550, 2021). "Mechanistic understanding of the processes responsible for regulating ALR, as we revealed here for INPP5K-related muscular dystrophy, may reveal unrecognized disease genes and disorders associated with defects in this pathway." (PMID 33119550, 2021). "Hypoglycosylation of α-dystroglycan occurs in the muscle of some patients with muscular dystrophy caused by INPP5K mutations, but this is not a universal finding because some individuals exhibit no detectable reduction." (PMID 33119550, 2021).
Lowe syndrome (4 papers, 2017 to 2023). "Mutations in different family members lead to specific and severe developmental disorders such as Lowe syndrome and Dent disease (OCRL), or MORM syndrome and Joubert syndrome (INPP5E), and most recently identified Marinesco–Sjögren Syndrome (MSS) caused by mutations in INPP5K." (PMID 33276499, 2020). "Specifically, we selected synaptojanin 1⁄2 (SYNJ1/2), INPP5E, INPP5J, oculocerebrorenal syndrome of Lowe (OCRL), INPP5B, and INPP5K, of which INPP5E/B and OCRL have already been shown to alter ciliary lipid composition." (PMID 38110903, 2023).
muscle disorder (2 papers, 2020 to 2021). "The INPP5K gene has been screened, through our customized next-generation sequencing (NGS) gene panel reported in more than 300 Italian patients from all over Italy affected by muscular disease." (PMID 33193651, 2020).
bladder cancer (1 paper, 2015). "Although INPP5K was the most significantly gene associated with bladder cancer, its convincingness was relatively weak because of its number of SNPs in this gene for bladder cancer." (PMID 25683757, 2015). "The strongest gene-based association was PLCD1 for pancreatic cancer and prostate cancer, PIK3C2B for breast cancer, and INPP5K for bladder cancer, respectively." (PMID 25683757, 2015).
colon adenocarcinoma (1 paper, 2022). "(B) DNA–RNA and RNA–protein correlations for representative complex and non-complex genes frequently gained (FAM210B and PRPF6) or lost (CTDNEP1 and INPP5K) in colon adenocarcinoma (COAD)." (PMID 36129397, 2022).
congenital cataracts (1 paper, 2023). "Considering that congenital cataracts are one of the most consistent phenotypes linked to INPP5K mutations in humans the high expression of inpp5ka in lens cells found in the RNA scope experiments is also of note." (PMID 37184573, 2023).
glioblastoma (1 paper, 2020). The most malignant astrocytic tumor (WHO grade IV). "INPP5K can be found either upregulated or downregulated in glioblastomas, relative to normal brain tissue; and, increased INPP5K expression in glioblastoma is associated with improved long-term survival." (PMID 33276499, 2020). "Some of the other 5-phosphatases have been reported to regulate tumourigenesis in other cancer types such as glioblastoma (INPP5K) and medulloblastoma (INPP5E), but have not been implicated in the pathogenesis of breast cancer to date." (PMID 33276499, 2020).
liver cancer (1 paper, 2020). An epithelial or non-epithelial malignant neoplasm that arises from the liver. "In this study, we found that INPP5K was lowly expressed in liver cancer and low expression of the INPP5K mRNA was associated with poor survival status and recurrence in liver cancer." (PMID 32420386, 2020). "In conclusion, low INPP5K mRNA expression is an independent risk factor for poor prognosis in liver cancer." (PMID 32420386, 2020). "Patients were divided into high and low INPP5K expression groups to explore the correlations between INPP5K expression and different clinical features of liver cancer." (PMID 32420386, 2020). "We compared the expression of INPP5K mRNA in liver cancer (n = 373) and normal liver (n = 50) tissue via box plots." (PMID 32420386, 2020). "In this study, we intend to assess the independent prognostic value of INPP5K expression for overall survival of liver cancer patients." (PMID 32420386, 2020). "INPP5K expression in liver cancer was obtained from The Cancer Genome Atlas Liver Hepatocellular Carcinoma (TCGA-LIHC)." (PMID 32420386, 2020). "Consistent with the results in the TCGA cohort, the mRNA expression of INPP5K was significantly downregulated in liver cancer tissues (n = 225) when compared with normal liver tissues (n = 220) in GSE14520 cohort (P ≤ 0.0001)." (PMID 32420386, 2020). "Our results showed that low INPP5K expression was correlated with poor outcomes in liver cancer patients." (PMID 32420386, 2020). "In this study, we explored the prognostic significance of INPP5K in liver cancer through bioinformatics analysis of data collected from The Cancer Genome Atlas (TCGA) database." (PMID 32420386, 2020). "The results indicated that INPP5K expression was lower in liver cancer (P = 0.013)." (PMID 32420386, 2020). "The decreased expression level of INPP5K was related to poor prognosis, which could act as an independent risk factor for OS and RFS in liver cancer patients." (PMID 32420386, 2020). "Low INPP5K expression was correlated poor outcomes in liver cancer patients by the Chi-square test." (PMID 32420386, 2020). "Our results demonstrated that INPP5K was lowly expressed in liver cancer." (PMID 32420386, 2020). "Our results indicated that INPP5K might be a biomarker for the diagnosis and prognosis of liver cancer." (PMID 32420386, 2020). "Univariate and multivariate Cox analyses demonstrated that INPP5K mRNA expression played a significant role in overall survival and relapse-free survival, which might be a useful biomarker and prognostic factor for liver cancer." (PMID 32420386, 2020). "This is the first study that suggested the relationship between INPP5K and clinical characteristics in liver cancer patients by mining TCGA database so far, which indicated that low INPP5K mRNA expression may serve as an independent prognostic factor for poor survival in liver cancer." (PMID 32420386, 2020). "Besides, our results showed that low INPP5K expression correlated significantly with poor RFS in liver cancer cases of nearly all clinical stage except the stage I, which suggested that INPP5K might not regulate the migration at the initiation of tumor formation." (PMID 32420386, 2020). "However, the prognostic significance of INPP5K expression in liver cancer has not been reported yet." (PMID 32420386, 2020). "Univariate and multivariate Cox analyses demonstrated that low INPP5K mRNA expression played a significant role in shortening overall survival (OS) and relapse-free survival (RFS), which might serve as the useful biomarker and prognostic factor for liver cancer." (PMID 32420386, 2020).
Marinesco–Sjögren Syndrome (1 paper, 2020). "Recently, causative INPP5K mutations have been identified in families with Marinesco–Sjögren Syndrome (MSS) in which affected individuals display congenital muscular dystrophy, cataracts and intellectual disability." (PMID 33276499, 2020).
neuroblastoma (1 paper, 2024). Neuroblastoma (NB) is the most common solid, extracranial childhood tumor. "Knockdown of INPP5K in the neuroblastoma-derived cell line N2A impaired their neuronal-like differentiation and interfered with protein glycosylation." (PMID 38559586, 2024).
Obesity (1 paper, 2023). Accumulation of substantial excess body fat. "Combined with our result that INPP5K expression is upregulated in the higher BMI MZ siblings, this suggests that the regulatory circuit we highlight here is a BMI-responsive pathological mechanism contributing to obesity-related traits." (PMID 37452040, 2023).
Stillbirth (1 paper, 2023). Death of the fetus in utero after at least 22 weeks of gestation. "Though the study was limited in ascertaining de novo from inherited variants, due to unavailability of paternal DNA, genes were reported by the authors that are either lethal, known to cause disease, or increase stillbirth risk (e.g., CCR5, FAT1, FLNB, INPP5K, MYO1C, PLOD2)." (PMID 36800380, 2023).
tumor (6 papers, 2015 to 2024). "In fact, Oncomine results show decreased expression of INPP5K in PCa compared to normal tissue, suggesting a possible tumor suppressor activity of INPP5K." (PMID 28915573, 2017). "Restoration of gene expression was detected for Myo1c and Inpp5k genes in the tumor samples at RNA and/or protein levels." (PMID 26170120, 2015). "Statistical analysis of qPCR results combined with subsequent gene mutation screening along with epigenetic and protein expression analyses suggested Inpp5k and Myo1c as the most prominent target tumor suppressor candidates in this region." (PMID 26170120, 2015). "The gene adjacent to Inpp5k, and the second candidate tumor suppressor gene identified in the present work, is the molecular motor myosin 1c (Myo1c)." (PMID 26170120, 2015). "According to Knudson’s theory of inactivation of tumor suppressor genes, if Hic1, Inpp5k and Myo1c are to behave as classical tumor suppressor genes, it is expected that both alleles of the genes be inactivated in the tumor material." (PMID 26170120, 2015). "Moreover, there are reports on tumor suppressor activity of other members of the gene families that INPP5K and MYO1C belong to." (PMID 26170120, 2015). "Moreover, other members of gene families that INPP5K and MYO1C belong to are suggested to function as tumor suppressor genes in a variety of cancer types." (PMID 26170120, 2015). "Hic1, Inpp5k, and Myo1c showed reduced expression in tumor samples irrespective of the presence or absence of physical deletion in the candidate region, suggesting the potential involvement of alternative gene silencing regulatory mechanism(s)." (PMID 26170120, 2015). "There is no earlier report on the potential tumor suppressor activity of INPP5K and MYO1C, however, overlapping roles in phosphoinositide (PI) 3-kinase/Akt signaling, known to be vital for the cell growth and survival, are reported for both." (PMID 26170120, 2015).
cancer (2 papers, 2015 to 2020). A tumor composed of atypical neoplastic, often pleomorphic cells that invade other tissues. "Inositol polyphosphate-5-phosphatase K (INPP5K) belongs to the family of phosphoinositide 5-phosphatases (PI 5-phosphatases), which have been reported to be associated with cell migration, polarity, adhesion, and cell invasion, especially in cancers." (PMID 32420386, 2020). "So far, there is no report on potential involvement of INPP5K in cancer progression." (PMID 26170120, 2015).
neurodevelopmental disorder (1 paper, 2021). A behavioral and cognitive disorder with onset during the developmental period that involves impaired or aberrant development of intellectual, motor, or social functions. "The pathomechanism explaining the disease mechanism remains unknown, however several others genes of the inositol phosphatase metabolism (e.g., INPP5K, FIG4, INPP5E, ITPR1) are correlated with phenotypes of neurodevelopmental disorders." (PMID 33168985, 2021).
INPP5K also shares sentences with these, for which no sentence is quoted: intellectual impairments (4 papers); Ataxia (2); brain abnormalities (1); Brain atrophy (1); brain malformations (1); breast carcinoma (1); Cerebellar atrophy (1); cervical squamous cell carcinoma (1); congenital myopathies (1); hereditary spastic paraplegia (1); infection (1); kidney disease (1); myopathy (1); pancreatic cancer (1); Parkinson disease (1); polyneuropathy (1); prostate carcinoma (1).